IL37 (interleukin 37)
Diseases named in the same sentence as IL37 in open-access papers (continued):
Sharing a sentence is not in itself a finding about the gene and the disease.
colorectal cancer (12 papers, 2013 to 2025). A primary or metastatic malignant neoplasm that affects the colon or rectum. "IL-37 inhibits the protective cytotoxic T-cell-mediated immune response in the colitis-associated colorectal cancer and B16-OVA models." (PMID 40583347, 2025). "Research has shown that IL-37 plays an important role in the intestinal mutation, proliferation, apoptosis and migration of colorectal cancer (CRC) cells." (PMID 40583347, 2025). "Here, we found that IL-37 transgenic (IL-37tg) mice were highly susceptible to colitis-associated colorectal cancer (CAC) and suffered from dramatically increased tumor burdens in colon." (PMID 35046386, 2022). "In human colorectal cancer reduced IL-37 expression was associated with disease progression and poor outcome." (PMID 31781119, 2019). "In colorectal cancer model, we showed that suppressed immune status and inactivated CD8+ T cells in IL-37tg mice, thus responsible for cancer susceptibility of IL-37." (PMID 35046386, 2022). "Similarly, colonic IL-37 expression is also significantly reduced in colorectal cancer tissues, possibly due to its role in neutrophil recruitment." (PMID 40191189, 2025). "Moreover, IL-37 expression is closely associated with overall disease-free status and survival in both NSCLC and colorectal cancer, further supporting the protective role of IL-37 in the mucosa during the development of malignancies." (PMID 40191189, 2025). "Furthermore, the findings from HCC align with observations in colorectal cancer, where both mRNA and protein levels of IL-37 are substantially reduced in colorectal cancer tissues compared to non-cancer tissues." (PMID 38312834, 2024). "Moreover, the regulatory role of IL-37 varies between gastric cancer and colorectal cancer, promoting carcinogenesis through the up-regulation of IL-37 in gastric cancer or the down-regulation of IL-37 expression in colorectal cancer within the local mucosa." (PMID 39206201, 2024). "The molecular mechanism and function of IL-37 in colorectal cancer (CRC) has been elusive." (PMID 35046386, 2022). "Moreover, the new defined inhibitory factor IL-37/SIGIRR in the cancer-immunity cycle is established as therapeutic targets in colorectal cancer." (PMID 35046386, 2022). "Additional factors might also be associated with IL-37 transgene expression, i.e., changes of the intestinal microbiota and subsequent changes of bile acid metabolism, as discussed for human PSC and colorectal cancer." (PMID 31781119, 2019). "Moreover, our data enhance knowledge regarding IL-37 and highlight the role of IL-37/SIGIRR signaling in the CRC, and these findings will aid in the development of new strategies for the treatment of colorectal cancer." (PMID 35046386, 2022). "Colorectal cancer exhibits substantially reduced IL-37 at both the mRNA and protein levels, compared to that of non-cancer tissues." (PMID 35186997, 2022). "Interleukin (IL)‐37 and neutrophils are considered to be involved in human cancer, but their prognostic significance in colorectal cancer (CRC) has not been elucidated." (PMID 30004182, 2018). "The observed inverse correlation between IL-37 expression in NSCLC and the depth of colorectal cancer invasion suggests that IL-37 may similarly regulate host immunity in the lung and gut, governed by the mucosal lymphoid-associated tissue immunological system." (PMID 40191189, 2025).
COVID-19 (12 papers, 2021 to 2025). A disease caused by infection with severe acute respiratory syndrome coronavirus 2. "Elevated circulating IL-37 levels were found in COVID-19 patients, with higher IL-37 levels being associated with shorter hospitalization periods." (PMID 39337246, 2024). "The potential involvement of IL-37 in suppressing the cytokine storm that contributes to poor prognosis and mortality in COVID-19 patients was studied." (PMID 35095801, 2021). "In relation to COVID-19, IL-37 has been suggested to be a potential treatment based on its anti-inflammatory profile to inhibit IL-1β, IL-6 and TNF, which are the main players of the cytokine storm." (PMID 34422917, 2021). "Concerning the results found in the mild COVID-19 subgroups, it was found that mild A group showed higher levels of SIgA, IL-10, and IL-37 than the mild B groups, as well as increased IFN-γ as compared to the negative and others groups." (PMID 33717074, 2021). "Based on these properties, we can putatively suggest that the positive correlations between IL-37 and other cytokines lead to the control of mucosal inflammatory response in the mild B COVID-19 subgroup." (PMID 33717074, 2021). "The role of IL-37 in COVID-19 is supported by the findings in influenza viral infection, showing that IL-37 ameliorates influenza pneumonia in vivo." (PMID 34422917, 2021). "In pulmonary infections, IL-37 modulates host responses by mitigating virus-induced hyperinflammation and inhibiting viral replication, as observed in COVID-19 and influenza, while also regulating immunopathology in Mycobacterium tuberculosis and fungal infections." (PMID 41293155, 2025). "The immunosuppressive signature attributed to IL-37 has been attracting attention in terms of COVID-19, since some authors have proposed that its use could minimize the inflammation associated with SARS-CoV-2 infection, including the cytokine storm." (PMID 33717074, 2021). "It has been reported that circulating IL-37 is elevated in COVID-19 infected patients." (PMID 34422917, 2021). "In the same way, the higher IL-37 levels observed in both severe and mild A COVID-19 subgroups could be involved in a mechanism of inflammatory control in the airways mucosa." (PMID 33717074, 2021). "However, in relation to the group mild B COVID-19 subgroup, it is possible to highlight other significant positive correlations between IL-37 and the cytokines IFN-α, IFN-γ, IL-6, and IL-10." (PMID 33717074, 2021). "Thus, low IL-37 plasma levels can be used to predict the severity of COVID-19." (PMID 41293155, 2025). "CXCL8, along with IL-37 and CRP, could be combined into a highly sensitive model to effectively differentiate severe cases from moderate ones in the COVID-19 population." (PMID 35037831, 2022). "IL-37 exerts significant anti-inflammatory and metaboregulatory effects, dramatically reducing cytokine secretion in macrophages and dendritic cells, with higher early IL-37 responses in COVID-19 patients leading to earlier viral RNA negative conversion." (PMID 35095801, 2021). "In addition, when COVID-19 patients were analyzed based on the illness severity (mild A, mild B, and severe) it was observed that severe COVID-19 group showed increased levels of SIgA, IFN-α, IFN-β, IFN-γ, and IL-37 as compared to the others groups." (PMID 33717074, 2021). "Higher early IL-37 responses were correlated with earlier viral RNA negative conversion, chest computed tomographic improvement, and cough relief in COVID-19 patients." (PMID 35095801, 2021). "Finally, a total of eleven differential factors related to COVID-19 disease severity were identified, including: TRAIL R1, IGFBP-1, IGFBP-4, VCAM-1, sFRP-3, FABP2, Transferrin, GDF15, IL-1F7 (also known as IL-37), IL-5Rα, and CD200." (PMID 34335566, 2021).
endotoxemia (12 papers, 2014 to 2023). "It is important to note that this does not rule out the possibility that anti-inflammatory effects linked to the nuclear function of IL-37 likely take place in humans and may influence MS, as we recently observed in endotoxemia in mice." (PMID 33391457, 2021). "To investigate the effect of IL-37 on the generation of mature IL-18, we also analyzed LPS-induced plasma IL-18 in mice subjected to endotoxemia." (PMID 31936823, 2020). "In mice subjected to endotoxemia, IL-37 inhibited plasma IL-1β (−78% compared to wild-type animals) and IL-18 (−61%)." (PMID 31936823, 2020). "In endotoxemia mice, pre-treatment with IL-37 reduced circulating and organ cytokine levels, and alleviated LPS-induced weight loss and hypothermia." (PMID 27941849, 2016). "The author clarified that mice with a transgenic expression of IL-37 (IL-37tg) were protected against endotoxemia, whereas IL-1R8-deficient IL-37tg mice were not." (PMID 35935954, 2022). "LV function was improved since myocardial inflammatory responses to endotoxemia in old mice were suppressed by IL-37, as the result of the attenuation of NF-κB activation and MCP-1 production following LPS stimulation in cardiac microvascular endothelial cells from IL-37tg mice." (PMID 30728750, 2019). "Furthermore, IL-37 plays a critical role in suppressing cardiodepressant cytokines, while it improves LV function in aging mice during endotoxemia through suppression of myocardial production of MCP-1 and cardiodepressant cytokines." (PMID 30728750, 2019). "Interestingly, recombinant IL-37 markedly up-regulated myocardial Klotho levels in old mice with or without endotoxemia." (PMID 37292905, 2023).
Hypertension (11 papers, 2017 to 2023). The presence of chronic increased pressure in the systemic arterial system. "Notably, new studies involving pro-inflammatory interleukin IL-18 and anti-inflammatory interleukins IL-37 and IL-38 have provided interesting new findings related to hypertension prevention." (PMID 34445357, 2021). "Moreover, in patients with arterial hypertension, alterations in IL-12, IL-23, IL-27, IL-35, and IL-37 concentrations are connected with the development of carotid atherosclerotic plaque." (PMID 34835476, 2021). "For example, even in the highest stage of hypertension, which is associated with overt atherosclerotic disease, plasma IL-37 levels reached values that were not higher than 50 pg/mL, which is consistent with the lower part of the upper IL-37 quartile in this study." (PMID 36834391, 2023). "Whether IL‐37 exerts a protective role in hypertension, autoimmune myocarditis, and heart failure has not been clearly investigated." (PMID 28548248, 2017).
plaque psoriasis (11 papers, 2019 to 2025). "The balance between TNFα, IL‐37 and IL‐17 expression may therefore be important in establishing plaque psoriasis inflammatory borders." (PMID 39157924, 2025).
Autoimmunity (10 papers, 2014 to 2024). The occurrence of an immune reaction against the organism's own cells or tissues. "Thus, IL-37 suppresses the autoimmunity in MG via direct target of follicular Th and B cells." (PMID 34248996, 2021). "Similarly, IL-37 is a cytokine for inflammation, autoimmunity, and other immunological disorders." (PMID 25214710, 2014). "Creating a stable Treg cell line, such as with our IL37 OE Jurkat cells, will provide a convenient model for analyzing Treg plasticity, helping to understand the molecular mechanisms that support FOXP3 expression and aiding in the development of therapeutics for autoimmunity and cancer." (PMID 36010641, 2022).
breast carcinoma (10 papers, 2017 to 2026). "The current review focuses on the correlation between clinical presentations and the expression of IL-35 and IL-37, as well as the potential underlying mechanism during the development of breast cancer in vitro and in vivo." (PMID 36483045, 2022). "The precise underlying mechanism of the IL-37 protective role during the development of breast cancer remains to be clarified." (PMID 36483045, 2022). "Much of the data on IL-37 and IL-38 comes from in vitro models or preclinical studies on various tumors; however, specific experimental data on breast cancer are scarce or insufficient and are still under investigation." (PMID 41596472, 2026). "For instance, in breast cancer, circulating IL-37 expression was reported to be highest in ER+/PR+/HER2+ patients compared to PR+ breast cancer patients, emphasizing a potential role in prognosis regulation through ER+/PR+/HER2+ signaling." (PMID 40444012, 2025). "This is consistent with the observation that reduced circulating IL-37 mRNA expression is accompanied by reduced circulating CD8+ Tc cells within breast cancer patients." (PMID 36483045, 2022). "Taken together, these data suggest IL-37 plays a critical protective role during the development of breast cancer via promoting M1 polarization and both the number and function of Tc cells in the breast cancer tissues." (PMID 36483045, 2022). "In conclusion, IL-35 seems to promote the development of breast cancer; whereas IL-37 protects the host during the development of breast cancer." (PMID 36483045, 2022). "A study utilized a mouse 4T1 breast cancer model illustrated that although IL-37 was successfully expressed in 4T1 cells after transduction with recombinant adenovirus and the secreted form was detected in the culture supernatant, the in vitro proliferation of 4T1 cells was not directly affected." (PMID 37928545, 2023). "There are few reports on the role of IL-37 in female breast cancer so far." (PMID 37928545, 2023). "IL-35 is inversely correlated the differentiation and prognosis in breast cancer patients; whereas IL-37 shows dual roles during the development of breast cancer, and may be breast cancer stage dependent." (PMID 36483045, 2022). "Importantly, the suppression of the development of breast cancer is abrogated in recipients with T cell deficient BALB/c nude mice, in the presence of exogenous IL-37 administration, suggesting the important anti-tumour role of IL-37β is T cell mediated." (PMID 36483045, 2022). "Moreover, IL-37 was unable to afford an increased survival rate to mice afflicted with breast cancer cells presumably because a highly metastatic cancer cell line (4TI) was employed." (PMID 29641433, 2018). "In mouse models of breast carcinoma, IL-37 decreased tumor growth in immunocompetent mice." (PMID 29641433, 2018). "In our laboratory, we are preparing a list of practical experiments that could be performed to directly test both IL-37 and IL-38 in breast cancer models (tumor cells, co-cultures with macrophages and lymphocytes) using these recombinant anti-inflammatory cytokines." (PMID 41596472, 2026). "Therefore, blocking IL-1 with IL-37 or IL-38 could represent a novel therapeutic strategy that, when combined with other treatments, could be beneficial in breast cancer." (PMID 41596472, 2026). "Substantially reduced circulating IL-37 mRNA has been detected within breast cancer patients irrespective of metastasis, compared to that of healthy controls, suggesting that IL-37 is protective during the development of breast cancer." (PMID 36483045, 2022). "IL-38 or IL-37 may serve as prognostic biomarkers in certain cancers, such as prostate and breast cancer; however, there are currently no clinical therapies targeting IL-37 or IL-38." (PMID 41596472, 2026).
breast carcinoma (continued). "A recent study verified that circulating IL-37 was highest in ER+/PR+/HER2+ breast cancer patients, compared to PR+, but not ER+/PR+ patients without metastasis, suggesting that IL-37 may influence the prognosis of breast cancer via ER+/PR+/HER2+ signaling." (PMID 37928545, 2023). "A possible explanation is that reduced circulating CD8+ Tc cells is due to increased recruitment of local CD8+ Tc cell infiltration in the breast tissue, suggesting that IL-37 may regulate host immunity via CD8+ Tc cells activity mediating direct and/or indirect cytotoxicity against breast cancer." (PMID 36483045, 2022). "However, the most critical issue is that there is no data available about the production of IL-37 in breast cancer tissue itself, which is rather urgently needed to confirm the role of IL-37 during the development of breast cancer in vivo." (PMID 36483045, 2022). "However, the involvement of IL-35 and IL-37 in breast cancer has not been rigorously reviewed." (PMID 36483045, 2022). "Interestingly, circulating IL-37 expression is highest for ER+/PR+/HER2+ breast cancer patients, compared to PR+ breast cancer, but not ER+/PR+ breast patients without metastasis, suggesting that IL-37 may also influence the prognosis via ER+/PR+/HER2+ signalling." (PMID 36483045, 2022).
colon carcinoma (10 papers, 2014 to 2024). "Previous studies have proclaimed that IL-37 affected bile acid metabolism which has been shown to contribute to squamous cell carcinoma-associated colon cancer." (PMID 37928545, 2023). "But the underlying mechanisms of IL-37 in colon cancer remain unclear." (PMID 28467774, 2017). "No obvious change in proliferation rate was observed through CCK8 in IL-37 stable expressing human LoVo colon carcinoma cells (LV-IL-37/LoVo) and control cells (LV-Ctrl/LoVo)." (PMID 35046386, 2022). "Our results showed that IL-37 plays an inhibitory role in colon cancer development and function as a novel prognostic indicator and a potential therapeutic target." (PMID 28467774, 2017). "We first evaluated the IL-37 expression in 186 pairs of colon cancer samples and their adjacent normal mucosa by real-time PCR, ELISA (Enzyme-linked immunoassay) and tissue microarrays." (PMID 28467774, 2017). "In the meantime, IL-37 also promoted colon cancer cell apoptosis and reduced cancer stem cell number." (PMID 28467774, 2017). "IL-37 is decreased in human colon cancer and capable of exerting anti-tumor activity by suppressing the β- catenin expression." (PMID 28467774, 2017). "Chemotherapeutic drugs treatment showed that IL-37 sensitize the colon cancer to these drugs, including 5-Fluorouracil, Cisplatin and Doxorubicin." (PMID 28467774, 2017). "Overexpression of IL-37 in colon cancer cell suppressed cell migration, invasion, proliferation, colony formation and cancer stem cells through suppressing β-catenin." (PMID 28467774, 2017). "Then the role of IL-37 on patient survival rates, colon cancer progression and their sensitivity to chemotherapy drugs were assessed." (PMID 28467774, 2017). "IL-37 was barely expressed in the colon cancer tissue but highly expressed in the adjacent normal tissue." (PMID 28467774, 2017). "IL-37 inhibited colon tumor formation in the mice model and sensitize the cancer cell to chemotherapy drugs." (PMID 28467774, 2017). "Here, we provided the evidences that IL-37 inhibits the colon cancer progression via β-catenin suppression." (PMID 28467774, 2017). "IL-37 expression was found in many cancer cells such as stroma of colon carcinomas, and ductal mammary carcinoma and also in blood monocytes, fully differentiated keratinocytes in stratum granulosum of skin, PBMC, and dendritic cell." (PMID 25177111, 2014). "Notably, in this study, colonic tumor IL-37 expression exhibits an inverse correlation with the depth of CRC invasion, consistent with CRC progression." (PMID 39206201, 2024). "Consequently, the signaling pathways for gastric cancer and colon cancer differ, suggesting the induction of different immune-regulatory mechanisms, particularly on IL-37 during tumorigenesis." (PMID 39206201, 2024). "It is believed that IBD patients with sustained intestinal epithelial inflammation are at increased risk of developing colon cancer or CRC, while the exist of IL-37 may suppress inflammatory environment as statement above." (PMID 37928545, 2023). "We further investigated whether IL-37 had a positive effect on the overproliferation of colon tumor cells." (PMID 35046386, 2022). "In addition, the right-sided location of colon carcinoma in IL-10KO mice indicates that transgene IL-37 expression additionally impacts bile acid metabolism which has been shown to be involved with PSC-associated colon carcinogenesis." (PMID 31781119, 2019). "However, the prognostic value of IL‐37 was shown using IHC in 186 colon cancer patients from a single center." (PMID 30004182, 2018). "Taken together, the data showed that the reduced IL-37 expression might contribute to colon cancer development and the poor outcomes." (PMID 28467774, 2017). "By inhibiting β-catenin expression, IL-37 impeded the colon cancer development." (PMID 28467774, 2017). "We found that IL-37 suppressed migration, invasion and proliferation of colon cancer cells." (PMID 28467774, 2017).